ALOX5 (arachidonate 5-lipoxygenase)
Diseases named in the same sentence as ALOX5 in open-access papers (continued):
Sharing a sentence is not in itself a finding about the gene and the disease.
infection (42 papers, 2011 to 2026). The state of being infected such as from the introduction of a foreign agent such as serum, vaccine, antigenic substance or organism. "For other lipoxygenases, it was reported that ALOX5−/− mice had lower virus titers in the lungs but greater susceptibility to the infection, enhanced immunopathology and decreased pulmonary function." (PMID 31013822, 2019). "Previous investigations indicate that Alox5−/− mice are more susceptible to infections and envenomation." (PMID 29247243, 2017). "As the Alox5−/− mice were more susceptible to infection than the 129sv, we evaluated the effect of LTB4 treatment on the genetically modified mice." (PMID 29247243, 2017). "Another was ALOX5, encoding lipoxygenase, which uses arachidonic acid to produce 5-hydroperoxyeicosatetraenoic acid and leukotriene A4, which has an established pathological role in inflammation and infection." (PMID 39478120, 2024). "The relevance of lipid mediators produced by 5-LOX, including LXA4, was demonstrated by the infection of mice deficient in this enzyme (Alox5-deficient mouse) that presented intense lymphocyte infiltration and high pro-inflammatory cytokine expression, and also accelerated mortality." (PMID 37446699, 2023). "However, the transcript levels of the genes encoding arachidonate 5-lipoxygenase (Alox5), which is involved in leukotriene (LT) biosynthesis, and constitutive Ptgs1 both declined in neutrophils on ST infection." (PMID 27363812, 2016). "In the infection group, the expression of Alox5 and Cox-2 was upregulated significantly, and the regulatory enzymes Lpcat1 and Lpcat2, which are involved in PC remodeling, were also significantly upregulated." (PMID 40463366, 2025). "The transcription of Cox-2, Alox5, Hpgds, and Plb1 was significantly upregulated, indicating that AA metabolism in the liver is markedly activated after infection." (PMID 40463366, 2025). "This is further given credence by the finding that varying rates of infection were observed for human variants for the LTA4H and ALOX5 loci, both of which interfere with LXA4 and LTB4 production." (PMID 37927821, 2023). "Several genes were significantly upregulated (Pla2g4a, Pla2g4c, Pla2g7, Ptgs1, Ptgs2, Pla1, Tbxas1) or downregulated (Alox5, Pla2g2d, Pla2g1b, Pla2g4b, Pla2g4f) during infection." (PMID 35812400, 2022). "Within MAP-infected macrophages, ALOX5 is downregulated, but COX2 is elevated between 8 and 24 h post-infection, and ALOX5, along with other immune-related genes, is downregulated 6 months post MAP inoculation." (PMID 34822384, 2021). "At the 3rd day post-infection, Alox5−/− mice treated with LTB4 exhibited similar amounts of α-defensin-1 compared to untreated 129sv-infected mice." (PMID 29247243, 2017). "BALF protein concentrations increased 129% in Alox5−/− mice, while 129sv mice exhibited an increase of 39% at days 1 and 3 post-infection." (PMID 29247243, 2017). "Of interest, LTB4 administration to Alox5−/− mice restored the expression of Defa1, and at the 3rd day post-infection, BALF of infected and LTB4 treated Alox5−/− mice exhibits comparable levels of α-defensin-1 to that of 129sv mice." (PMID 29247243, 2017). "Compared to 129sv mice, the levels of TNF-α, IL-1α, and MIP-1α were 76%, 58%, and 42% higher in Alox5−/− mice at the 1st day post-infection." (PMID 29247243, 2017). "The Alox5−/− mice exhibited a 5- and 9-fold higher lung bacterial burden compared to the wild-type, at days 1 and 3 post-infection, respectively." (PMID 29247243, 2017). "Infected Alox5−/− mice treated with LTB4 exhibited 66% survival at the 7th day post-infection, compared to 0% survival of vehicle-treated infected Alox5−/− mice." (PMID 29247243, 2017). "Infected Alox5−/− mice showed impaired bacterial clearance, increased lung inflammation, and succumbed to the infection by the 7th day." (PMID 29247243, 2017).
infection (continued). "Following infection, 100% of the Alox5−/− mice died within the first 5 days, while 85% of the wild-type mice survived 7 days post-infection (wild-type animals survived for at least 14 days post-infection, the last observed time-point, data not shown)." (PMID 29247243, 2017). "When infected with A. xylosoxidans, 129sv produce increased levels of α-defensin-1 compared to infected Alox5−/− mice, on 1st day post-infection." (PMID 29247243, 2017). "Our results show that lipoxin treatment at the time of infection significantly prolonged survival of both infected Alox5−/− mice (MST 17.5 vs. 3.5 days) and WT mice (MST 20 vs. 5 days) for 15-epi-LXA4-treated and PBS-treated groups, respectively." (PMID 23613965, 2013). "Consistent with this, il12a, il12b, ifng, il6, il17a mRNA expression were considerably increased in the brains of P. berghei ANKA-infected Alox5-KO vs. WT mice at 5 days after infection." (PMID 23613965, 2013). "To evaluate this possibility, we enumerated CD4+ and CD8+T cells, as well as IFN-γ+ cells in the brains of P. berghei ANKA-infected WT and Alox5−/− mice 5 days after infection." (PMID 23613965, 2013). "Alox5−/− mice had significantly increased serum levels of both cytokines 3 days after infection, as compared to WT mice." (PMID 23613965, 2013). "After 14 days of infection, there were 257 genes with greater expression in nociceptor-ablated mice (e.g., Vegfa, IL1a, IL1b, and Tnf) compared to 219 genes with greater expression in control mice (e.g., Alox5, Car2, Ccl5, Elane, and Mmp8)." (PMID 37845223, 2023). "Alox5−/− mice exhibit suppressed inflammation in response to infection or tissue injury." (PMID 31440260, 2019). "As an answer to these questions, the infection of mice deficient for Toll-like receptor 2 (TLR2), TLR4, IL-10, arachidonate 5-lipoxygenase (ALOX5), or arachidonate 15-lipoxygenase (ALOX15) with the M. tuberculosis Δnrp strain showed the same phenotype as WT mice." (PMID 30381350, 2018). "Since AlvMΦs prevent the upregulation of the cysLT pathway genes in T1AECs, AlvMΦs may confer resistance of T1AECs to infection by maintaining the ALOX5 promoter in a methylated state." (PMID 28085958, 2017). "We have previously noted that levels of ALOX5 were decreased in VN1203 infection in mice, and suggested that this may reflect the increased disease, supporting our observations in this study." (PMID 22074594, 2011). "Expression of genes within the periapical lesion after 14 days of infection was confirmed with real time PCR, where nociceptor-ablation resulted in a significant upregulation of IL1a (p = 0.01), Tnf (p = 0.01), and Nlrp3 (p < 0.01), whereas ablated mice had reduced expression of Alox5 (p = 0.03)." (PMID 37845223, 2023). "We found that, after infection, immature C57BL/6 mice showed increased lung cysLT levels and rare Alox5+ and Alox5ap+ cells in the airway epithelium with a triangular or bottle-like shape typical of tuft cells." (PMID 41573550, 2025). "Compared to 129sv, the Alox5−/− mice showed a small reduction in the BALF neutrophil counts at day 1, but a significant increase in neutrophils at day 3 post-infection." (PMID 29247243, 2017). "We observed that at the 1st day post-infection, treatment with LTB4 rescued the expression of Defa1 in lungs of infected Alox5−/− mice." (PMID 29247243, 2017). "At the 1st and 3rd day, infection with A. xylosoxidans induced significant release of TNF-α, MIP-1α, IL-1α and MCP-1 in both 129sv and Alox5−/− mice." (PMID 29247243, 2017). "Irrespective of the infection, Alox5−/− mice demonstrated higher production of PGE2 than the 129sv mice." (PMID 29247243, 2017). "The fact that Alox5 gene was downregulated during infection may account for the lack of detection of leukotrienes." (PMID 35812400, 2022). "However, at the 3rd day post-infection, only levels of MIP-1α were higher in the Alox5−/− mice." (PMID 29247243, 2017).
infection (continued). "However, as all Alox5−/− mice succumbed to the infection within 5 days, we could not measure PGE2 production after this time-point." (PMID 29247243, 2017).
cardiovascular diseases (13 papers, 2015 to 2026). "The arachidonate 5-lipoxygenase (ALOX5) specificity protein 1 (Sp1) promoter tandem repeat polymorphism is associated with enhanced cardiovascular disease (CVD) risk." (PMID 42141771, 2026). "ALOX5 may become a promising therapeutic target for human cardiovascular diseases treatment." (PMID 40781109, 2025).
neurodegenerative disease (11 papers, 2019 to 2025). A disorder of the central nervous system characterized by gradual and progressive loss of neural tissue and neurologic function. "Numerous evidence also indicated that PARP1, SCD, AR, ALOX5, HIF1A are critical involved in HD or neurodegenerative diseases." (PMID 38918688, 2024). "ALOX5, a key rate-limiting enzyme in AA metabolism, is responsible for catalyzing the conversion of 5-hydroperoxyeicosatetraenoic acid to LTA4, thus contributing to the occurrence and progression of inflammation and degenerative diseases." (PMID 38007425, 2023).
bacterial infections (5 papers, 2019 to 2023). "The downregulated proteins were related to the reduction in markers of inflammation (e.g., Alox5, Lbp, C5, Il36b, and Mmp8) and bacterial infections (e.g., Masp2, Mbl1, Krt34, and Cfd)." (PMID 38030636, 2023). "Further, we used SwissTargetPrediction to predict that its main targets are ALOX5, MCL1, and SLC6A4, and find that it can inhibit bacterial biofilm formation and reduce bacterial infection of cells." (PMID 37275170, 2023).
metabolic disorders (5 papers, 2017 to 2025). "ALOX5 and its polymorphisms have been explored as first-line candidates in a wide variety of inflammatory diseases including metabolic disorders, asthma,cardiovascular diseases, neurodegeneration, and cancer." (PMID 32093765, 2020). "The arachidonate 5-lipoxygenase (ALOX5) pathway has been investigated in diverse chronic inflammatory diseases including metabolic disorders." (PMID 32093765, 2020).
neurological disorders (5 papers, 2021 to 2025). "ALOX5 is negatively associated with neurological disorders, as 5-LOX is upregulated in neuronal tissue during AD." (PMID 40666111, 2025).
adenocarcinoma (1 paper, 2021). A common cancer characterized by the presence of malignant glandular cells. "In contrast to SAA, ALOX5 transcript expression was significantly reduced in adenocarcinoma tissue biopsies in both the unpaired and paired analysis." (PMID 34203378, 2021). "The SAA/ALOX5 ratio was significantly increased in adenocarcinoma compared to control biopsies and this ratio strongly correlated with MPO-positive neutrophils in adenocarcinoma." (PMID 34203378, 2021).
vascular disorder (1 paper, 2023). A general term used to describe any disease affecting blood vessels]. "There are six known functional LOX genes in humans (ALOX5, ALOX12, ALOX12B, ALOX15, ALOX15B, ALOXE3), but only three of them, 5-LOX, 12-LOX (platelet-type), and 15-LOX (reticulocyte-type), appear to be important for vascular disorders." (PMID 36675152, 2023).
ALOX5 also shares sentences with these, for which no sentence is quoted: osteoarthritis (8 papers); Insulin resistance (7); acne (6); ischemia (6); peritonitis (6); inflammation (5); type 2 diabetes mellitus (5); allergic rhinitis (3); Astrocytoma (3); brain tumors (3); carotid atherosclerosis (3); coronary artery disease (3); dermatitis (3); esophageal adenocarcinoma (3); injury (3); liver cancer (3); metabolic syndrome (3); pulmonary hypertension (3); tauopathy (3); type 1 diabetes (3); acute liver failure (2); airway hyperresponsiveness (2); allergic asthma (2); amyloidosis (2); cardiac hypertrophy (2); clear cell renal cell carcinoma (2); Cognitive impairment (2); colorectal adenoma (2); Crohn disease (2); Diabetic Nephropathy (2).
A further 128 diseases each share a sentence with ALOX5 in 2 papers or fewer.